IGFBP1 (insulin like growth factor binding protein 1)
Diseases named in the same sentence as IGFBP1 in open-access papers (continued):
Sharing a sentence is not in itself a finding about the gene and the disease.
tumor (continued). "Although clear evidence that tumour growth or migration is stimulated by IGFBP-1 is still lacking, IGFBP-1 has also been repored to have IGF-independent actions, such as activating α5β1 integrin." (PMID 28143425, 2017). "The compared with adjacent non-tumorous tissues, we found a higher level of RBM15, IGFBP1, RBMX, FTO, and ALKBH5 in all five STAD tissues, RBM15, FTO and ALKBH5 were overexpressed in STAD tumor tissues, while the expression of IGFBP1, RBMX was not changed in STAD tumor tissues." (PMID 37019148, 2023). "To determine whether IGFBP1 contributes to tumor cell survival in the vasculature of lung tissues during metastasis, we implanted luciferase‐expressing A549 cells with or without IGFBP1 into NOD/SCID mice via tail vein injection and monitored tumor cells in lung tissues in real time." (PMID 37296072, 2023).
cancer (95 papers, 2003 to 2026). A tumor composed of atypical neoplastic, often pleomorphic cells that invade other tissues. "Several studies have reported a correlation between circulating levels of IGF-1 and IGFBP-1 in healthy people and the risk of cancer development." (PMID 28143425, 2017). "High level of circulating IGFBP-1 was associated with poor all-cause mortality and cancer specific death in colorectal cancer patients (CRC)." (PMID 26217584, 2015). "Elevated plasma IGFBP-1 levels in cancer patients are associated with reduced Tex and enhanced intratumoral T cell responses, highlighting galactose as a potential dietary strategy to improve cancer immunotherapy." (PMID 41488640, 2025). "Understanding the involvement of IGFBP1 in various cancers and its association with immune and stromal components may provide valuable insights for the development of novel therapeutic strategies, leading to improved patient outcomes." (PMID 38700505, 2024). "Interestingly, IGFBP-1 has also been related to diabetes-related diseases, catabolism, and cancer, and further studies are needed to explore the specific types of mortality associated with s-IGFBP-1 levels." (PMID 37298072, 2023). "Among them, IGFBP1 and 3 were shown to be associated with cancer risk or outcome." (PMID 27579675, 2016). "PPARƔ primarily inhibits the growth of cancer cells; emodin decreases IGFBP1; cladosporol, rosiglilazone and a bis-indole PPARƔ ligand induce p21; and thiazolidinediones (TZDs) decrease an insulin receptor via PPARƔ/Sp1 in cancer cell lines." (PMID 39858066, 2025). "We selected IGFBP1, which had differential expression in most cancers and larger fold changes to further visualize its expression in 10 types of cancers and normal tissues, and presented in the form of mean ± standard deviation." (PMID 37088808, 2023). "Matrix metalloproteinase 7 (MMP-7), which is produced in excess by cancer cells, cleaves IGFBP1, -2, -4, -5, and -6 and results in IGF signaling that supports cancer cell growth and survival." (PMID 36465383, 2022). "The IGFBP-1 level in serum of patients with malignant tumors (41.26 ± 1.32) was higher compared to patients with benign tumors (32.90 ± 1.86) (P=0.0004)." (PMID 36713521, 2022). "By regulating the bioavailability of the type-1 IGF receptor (IGF1R) ligands, IGF-1 and IGF-2, the IGF binding proteins (IGFBP-1 to -6) play essential roles in cancer progression." (PMID 35597813, 2022). "A literature‐based survey clearly shows that the association between IGFBP2–3 and cancer was widely studied, while less studies were done on the remaining IGFBP family members (IGFBP1, IGFBP4, IGFBP5, and IGFBP6)." (PMID 35546443, 2022). "Insulin-like growth factor-1 (IGF-1) and the IGF binding protein 1 (IGFBP-1) expressions have been shown to play a vital role in cancer biology, including endometrioid endometrial cancer (EEC)." (PMID 36544136, 2022). "IGFBP-1's biological effects in cancer have been discovered to be reliant on its phosphorylation status, as well as on IGF-dependent and -independent pathways." (PMID 36157216, 2022). "The effects of the M2-like phenotype have been more closely linked to cancer progression and metastasis and therefore patient prognosis with SPINK1, LAMC2, IGFBP1, and IL-23A gene expression." (PMID 34732817, 2021). "Studies have shown that lncRNAs participate in mediating the occurrence and progression of cancer by targeting IGFBP1, thus becoming a new therapeutic target for cancer." (PMID 34238292, 2021). "The results showed that STAD patients had the highest rates of IGFBP1–7 genetic alterations compared with other cancer types, with 80 of 440 patients (18.8%) having such alterations according to TCGA data." (PMID 34745945, 2021). "IGFBP1 has been shown to be a metabolic regulator under stress conditions in some cancer types, and enhanced glycolytic capacity is considered to be a hallmark of cancer." (PMID 34350183, 2021).
cancer (continued). "The upregulated expression of IGFBP1 in NPC samples indicates that in the NPC cases, there are some regulations that cause the increased proliferation of cancer cells." (PMID 32986356, 2020). "Meanwhile, findings on the correlation between the IGFBP1 and prognostic value in different types of carcinoma were inconsistent." (PMID 33282953, 2020). "IGFBP1 has independent inhibitory effects on cancer cell growth and metastasis in preclinical studies, both directly and through local modulation of other components of the IGF axis." (PMID 27152521, 2016). "Studies demonstrated that expression of IGFBP1 was associated with p38 MAPK signaling and involved in cancer cell growth." (PMID 27036874, 2016). "Nevertheless, the insight true role of IGFBP1 in cancer cell biology, especially in growth and progression of HCC, still remains controversial." (PMID 27036874, 2016). "Comparative expression profiling of human IGFBP genes in different cancer cells demonstrated that IGFBP-1, -3 and -5 are primary 1, 25-D3 target genes." (PMID 23690781, 2013). "Of 19 validated markers that were identified all were found in cancer peritoneal fluid and a subset of 7 were quantified in serum, with one of these proteins, IGFBP1, newly validated here." (PMID 20559444, 2010). "When IGFBP-1 was added to preintervention serum, LNCaP cancer cells underwent apoptosis; whereas, when IGF-I was added to postintervention serum, the reduction in growth was eliminated." (PMID 20885914, 2010). "(E) SKM contractile activity-induced decreases in IGF-1, IGFBP-2, and insulin levels and increased IGFBP-1 and -3 levels may also help to limit cancer development in SKM." (PMID 38928185, 2024). "Moreover, increasing studies indicate the expression and prognostic value of IGFBP-1 in serum/tissue of patients with cancer remains equivocal and even controversial." (PMID 38246959, 2024). "In addition, as a secreted protein, aberrant expression in circulating and potential clinical implications of IGFBP-1 in patients with cancer have been reported." (PMID 38246959, 2024). "An increase in insulin may also reduce the inhibitory effects of IGFBP‐1 on cancer cell growth and migration." (PMID 38477501, 2024). "Studies have demonstrated that the IGFBP family (IGFBP1–6) are relevant in many cancers." (PMID 35546443, 2022). "One study showed that IGFBP-1 was associated with long-term all-cause and cancer mortality but not cardiovascular events." (PMID 35127852, 2021). "The expression of IGF2BP1/2/3 was significantly reduced in m6ACluster B, which revealed that IGFBP1/2/3 may play a vital role in cancer development." (PMID 34733275, 2021). "IGFBP1 plays an essential role in the development and progression of cancer." (PMID 32986356, 2020). "Similarly, matrix metalloproteases (MMP2, MMP7, and MMP9) whose expression is high in the peritumoral stroma and cancer cells can mediate proteolysis of IGFBP1, -2, -3, -4 and -6." (PMID 32414222, 2020). "Analysis of the cell secretome revealed specific cell-type differences (MDA-MB-231 cells: increased cancer attenuator follistatin and reduced pro-inflammatory cytokines IGFBP-1, MCP-1, MIP-1α, IL-6; MCF7: increased cancer signals osteopontin, sHER-2, VEGF-A, uPA, EGF amongst others)." (PMID 30603045, 2018). "By binding and sequestering IGF-1, IGFBP-1 antagonized IGF-1 which could stimulate the proliferation of cancer cells." (PMID 28143425, 2017). "An interesting study using IGFBP-1 deficient mice demonstrated that IGFBP-1 can function as a cell survival factor by repressing TGFβ activation, but the relevance of this effort for cancer cell survival is not understood." (PMID 25866791, 2015). "In this and subsequent other studies, serum IGFBP-1 also did not demonstrate a predictive value for cancer risk in CRC, NSCLC, and endometrial cancer." (PMID 26217584, 2015).
cancer (continued). "In particular, growth-regulated protein (GRO), ENA-78/CXCL5, TIMP-2, and leptin were strongly up-regulated in malignant seroma, whereas IGFBP-1 (insulin-like factor binding protein-1), IL-3, IFN-γ, FGF-9 and IL-16 were down-regulated in malignant versus benign seroma fluid." (PMID 26361584, 2015). "IGFBP1 is secreted from the liver and is hypothesized to exert a protective role in the development of cancer and cardiovascular diseases." (PMID 25202454, 2014). "Overall, IGFBP-1 levels were higher among the cancer cases than among control women." (PMID 14583772, 2003). "For example, circulating IGFBP1 and IGFBP2 appear to be involved in regulating acute bioavailability of IGFs, and when their expression is inhibited, they may increase the mitogenic activity, thereby increasing the risk of cancer." (PMID 37088808, 2023). "Thus, IGF-1 and IGFBP-1 may play important roles in modulating the effect of exercise serum on cancer cell growth and survival." (PMID 28481292, 2017). "Furthermore, no previous intervention study has been conducted to examine whether an exercise regimen alone can elicit favorable changes in both IGF-I and IGFBP-1 levels for cancer prevention in healthy men." (PMID 20885914, 2010). "Thus, we investigated the effect of mild aerobic exercise training at LT level on the circulating levels of IGF-I, IGFBP-1, and IGFBP-3 to determine an optimal exercise intervention that can induce favorable changes in IGF-I and IGFBP-1 levels for cancer prevention in healthy men." (PMID 20885914, 2010). "These target genes, including IGFBP1, WNT1, WNT10B, TGFB1, PCK1, and SLC2A3, are critical for cancer cell proliferation and metastasis." (PMID 42311859, 2026). "High-intensity resistance exercise reduces IGFBP-1 and IGFBP-3, which are involved in cancer cell growth, reduces cholesterol, and enhances NKCA, which kills cancer cells." (PMID 39156757, 2024). "Specifically, IGFBP1/3/4/5/6 positively regulated EMT (p < 0.05), which was consistent with previous results in pan‐cancer and GSE27612." (PMID 37199034, 2023). "The role of IGFBP-1 as a transporter of IGF-1, and its RGD region, in activating integrin receptors in various cancer cells is well-known." (PMID 34531382, 2021). "The involvement of IGFBP1, TIMP1, SPP1, IGFBP3, and STC2 in mediating chemotherapy resistance in various cancers have been extensively studied." (PMID 34737677, 2021). "The gene set enrichment analysis revealed that these interacting proteins also interacted with cancer-related proteins, including KISS1, TIMP2, MMP11, IGFBP1, EGFR, and CDKN1C." (PMID 32117443, 2020). "Additionally, the emerging non-coding RNAs (ncRNAs) including microRNAs (miRNAs) and long non-coding RNAs (lncRNAs) have been demonstrated to be involved in the mediation of cancer onset and progression by targeting IGFBP1 and thus could become novel therapeutic targets of cancers." (PMID 29954406, 2018). "IGFBP-1 interacts with several other proteins in addition to ligands IGF-I and IGF-II and plays an important role in the development and progression of cancer." (PMID 27057199, 2016). "Thus, IGFBP-1 may have dual effects on cancer progression depending upon the environment contexts." (PMID 27057199, 2016). "Analysis of data from The Cancer Genome Atlas (TCGA) using the cBIO portal across most cancer types shows genomic alterations in IGF ligands (IGF1, 2), receptors (IGF1R, IGF2R), binding proteins (IGFBP1–6), and IRSs (IRS1, 2, 4); this representing 18 genes." (PMID 25964777, 2015). "It was suggested that one of the mechanisms involved may be an increase in circulating IGFBP-1 (IGF binding protein-1) and a decrease in serum IGF-I, resulting in reduced cancer cell growth." (PMID 39766992, 2024). "Finally, RT-PCR and WB showed that CDH17, IGF2BP1, IGFBP1, ABCC2, and HMGA2 were differently expressed between human lung fibroblast (HLF) cells and cancer cells." (PMID 35903696, 2022).
cancer (continued). "In addition, the core genes IGFBP1, FBN1, and SERPINA1 selected in this study have also been reported to be involved in the regulation of cancer cell migration and invasion." (PMID 34692659, 2021). "Previous studies have demonstrated that HNF-1β regulates the gene/protein expression such as annexin A4, osteopontin, uridine diphosphate (UDP)-glucuronosyl transferase 1A1 (UGT1A1), and insulin-like growth factor-binding protein 1 (IGFBP-1), which are vital for cancer progression." (PMID 34659566, 2021). "It was confirmed that induction of CHOP regulated the BCL-2 family to trigger caspase-3/GSDME dependent pyroptosis as well as depression of glycolysis by restraint of the AKT–GSK3β–IGFBP1 axis, suggesting a potential role of CBD in modulating cancer cell PCD and metabolism." (PMID 34350183, 2021). "IGFBP-1 is one of six IGF binding proteins that bind to and stabilize IGF proteins in circulation; they can have both positive and negative effects on IGF function, but IGFBP-1, specifically, has been reported to inhibit IGF-1 promotion of cancer progression." (PMID 32469992, 2020). "Although we additionally expected to observe a decrease in IGF-1, which is associated with cancer risk and aging, declines in IGF-1 and IGFBP-1 in the evening did not quite reach statistical significance (both p = 0.11)." (PMID 31151228, 2019). "IGFBP1 levels were significantly higher in cancer serum (p-value = 0.0097) while MMP9 levels were not (p-value = 0.20)." (PMID 20559444, 2010). "Whether exercise induces desirable (i.e., downregulation of IGF-I and upregulation of IGFBP-1) or undesirable (i.e., up-regulation of IGF-I and down-regulation of IGFBP-1) effects on cancer prevention is highly dependent on training intensity." (PMID 20885914, 2010). "Most terms suppressed by the words > 5 rule were found to be valuable terms that did not need to be suppressed, e.g. "Carcinoma of the Head and Neck", "insulin-like growth factor binding protein 1"." (PMID 20618981, 2010). "Another possibility would have been an increase in IGFBP-1 levels due to elevated cortisol, which stimulates hepatic IGFBP-1 synthesis, and which might reflect greater psychological stress among the cancer patients, for example." (PMID 14583772, 2003). "IGFBP-1, a secreted phosphoprotein, is generally highly phosphorylated and inhibitory to IGF action; however a hypophosphorylated form of IGFBP-1 can potentiate IGF-1-mediated cell proliferation, and IGFBP-1 is known from non-cancer studies to promote migration through integrin signaling." (PMID 35597813, 2022). "Additionally, nanoG also triggers various cancer stem cell markers and chemokine receptors, such as C-X-C motif receptor 4 (CXCR4), CD133, aldehyde dehydrogenase 1 (ALDH1), and insulin-like growth factor (IGF)-binding protein 1 (IGFBP1)." (PMID 32443915, 2020). "Specifically, CTD-2218G20.2 was predicted to interact with 86 proteins (Pearson correlation coefficient, PCC > 0.3), some of which, including PSG4, PSG5, and PSG7, could also interact with cancer-related proteins, including KISS1, TIMP2, MMP11, IGFBP1, EGFR, and CDKN1C." (PMID 32117443, 2020). "PXR’s implication for playing a role in human cancer metastasis may also stem from it being shown to regulate morphology and cell motility via the signaling axes of PXR GADD45β-p38MAPK and PXR-HNF4ɑ-insulin-like growth factor-binding protein 1 (IGFBP1)." (PMID 33076284, 2020). "Among six high-affinity IGFBPs, which are IGFBP-1 through 6, IGFBP-3 is the most extensively investigated IGFBP species with respect to its IGF/IGF-I receptor (IGF-IR)-independent biological actions beyond its endocrine/paracrine/autocrine role in modulating IGF action in cancer." (PMID 32443727, 2020). "However, in the context of IGFBP-1 and all-cause mortality, IGFBP-1 has been proposed to influence mortality through cancer, and we cannot rule out that poststroke cancer may confound the effect on mortality." (PMID 37298072, 2023).
cancer (continued). "It is interesting to show that the expression of IGFBP1 and IL8, a chemokine activated by CXCR2, were also up-regulated in this present study, thus it is speculated that the BLE may have an anticancer property that may involve the mediation of cancer cells senescence." (PMID 27635343, 2016). "The results showed that, except for IGFBP1 and IGFBP2, the expression of other IGFBP genes was significantly correlated with MSI in several cancer types, and the vast majority also showed negative correlation." (PMID 37088808, 2023).